IFNG (interferon gamma)
Diseases named in the same sentence as IFNG in open-access papers (continued):
Sharing a sentence is not in itself a finding about the gene and the disease.
latent infection (97 papers, 2006 to 2025). "Another possible cause for the decrease in IFNγ production could be the production of the Tbet+GATA3+ double positive TH1 cells we observed during the latent infection." (PMID 35186781, 2021). "Against the backdrop of the active immunity in latent infection, gene expression analysis using IFNG as a singular readout for T cell activation had limitations." (PMID 41044129, 2025). "The existing tests (the tuberculin skin test and the interferon-gamma release assay) are useful to distinguish between active and latent infections." (PMID 37686061, 2023). "The methylation status at the -53 CpG site of the IFNG promoter in individuals with latent infection (LTBI), TB and HD was determine by pyrosequencing." (PMID 36743307, 2023). "For example, the Rv1759c gene encodes the Wag22 antigen of the pe_pgrs family, which possess fibronectin activity and is involved in the maintenance of latent infection in a chronic infection model, inducing the production of high levels of interferon gamma." (PMID 37374997, 2023). "Here, we use murine gammaherpesvirus 68 (γHV68) to demonstrate that ABCs remain elevated long-term during latent infection and express IFNγ and TNF." (PMID 36477199, 2022). "During latent infection (35 days and 150 days p.i.), a significantly increased proportion of ABCs continued to express IFNγ and TNF compared to naïve mice, though the proportion of ABCs expressing IFNγ and TNF was decreased compared to acute infection." (PMID 36477199, 2022). "Our previous work showed that injection of IFNγ DNA into wild-type (WT) mice increased primary and latent infection in latently infected mice, while injection of CSF-1 DNA reduced primary and latent infection in these mice." (PMID 34653236, 2021). "Tuberculin skin test (TST) and interferon-gamma (IFN-γ) release assays cannot differentiate latent infection from active disease and a decreased sensitivity has been reported in children living with HIV8,9." (PMID 34162973, 2021). "MHV-68 shows persistent infection in IFNγ−/− or IFNγ receptor−/− mice, indicating a role of IFNγ in limiting the lytic infection or inhibiting reactivation from latent infection." (PMID 31921215, 2019). "An overly intense IFNγ+CD4+ T cell response is the most important immunological parameter distinguishing the active disease from latent infection in these people." (PMID 28646367, 2017). "Reactivation of latent infection into the active disease can be attributed to aggravated anti-Mtb IFNγ+CD4+ T cell responses." (PMID 28646367, 2017). "As previously observed, latent infection of control mice with MHV68 was associated with an increase in circulating levels of TNFα, IL-6, IL-12 and IFNγ compared with uninfected mice." (PMID 25599590, 2015). "These UL138-specific CD4+ T cells are able to mediate MHC class II restricted cytotoxicity and, importantly, show IFNγ effector function in the context of both lytic and latent infection." (PMID 24130479, 2013). "This possibly reflects the spectrum of IFNγ secretion as an individual progresses from control of latent infection to active TB disease." (PMID 22778764, 2012). "Current generation interferon-gamma release assays cannot distinguish immune responses among patients with latent infection, prior active disease, and current active disease when performed using peripheral blood specimens." (PMID 20302657, 2010). "The analysis highlighted the potential utility of interferon-gamma release assays as confirmatory tests for latent infection, after positive tuberculin tests in persons from countries where BCG is repeatedly administered." (PMID 18534007, 2008). "As IFNG gene expression analysis yielded some encouraging results but retained ambiguity due to the pre-existing immunity to latent infection, we further investigated whole transcriptome changes in the two stage II elephants that had received the full vaccine doses at extended intervals." (PMID 41044129, 2025).
latent infection (continued). "While IFNγ is important in host defense against C. neoformans infection, clinical data indicate that questions remain as to the role of IFNγ in each stage of C. neoformans disease progression—from latent infection to disseminated cryptococcal meningitis." (PMID 36983532, 2023). "Since higher levels of TNF/IFNγ have been previously reported in T cells of patients with latent infections like CMV26, we hypothesized that this phenomenon is suggestive of antigen-experienced T cell exhaustion, which is concordant with DE genes." (PMID 35411050, 2022). "Our data corroborate this view, since rec-MVA induced strong effector CD4+ T cells producing IFNγ which may have been consumed to control the latent infection." (PMID 31921215, 2019). "Its detection in isolation however is not a sufficient indicator of a protective immune phenotype as those with latent infection and a positive IFNγ release assay status can progress to active disease and IFNγ secretion can also be detected in samples from patients with active disease." (PMID 20609237, 2010). "Similarly, we have shown that ocular infection of WT mice with a recombinant virus expressing IL-4 (HSV-IL-4), which promoted macrophage responses toward M2, was more efficacious against both primary and latent infection than mice infected with a recombinant virus expressing IFNγ (HSV- IFNγ)." (PMID 34653236, 2021). "Interestingly, latent infection with MHV68 rescued HOIL-1 deficient mice from lethality during Listeria infection and induced high levels of the protective cytokine, interferon-gamma (IFNγ)." (PMID 25599590, 2015). "It has been demonstrated that antigen-specific expression of TNFa in theabsence of IFNg on CD4+ T cells in Mtb-infected patientsstrongly correlates with the potential to develop active TB, while the opposite phenotypeis supportive of latent infection." (PMID 39257997, 2024). "We did not see an increase in the percentage of TREG cells throughout the course of the latent infection that was concomitant with the increase in the TH1 cell population, thus it seems unlikely that the TREG cells are dampening the TH1 cell IFNγ production." (PMID 35186781, 2021). "It is unclear why CD4+ T cell responses to HCMV lytic antigens appear to be dominated by IFNγ producing cells, while CD4+ T cells, which recognise antigens, expressed during latent infection predominantly secrete cIL-10." (PMID 24130479, 2013). "When we compared healthy controls with latent infection (TST+) similar and much more marked effect of IFNγ +874 TT genotype was observed." (PMID 19274101, 2009). "In the latent infection context, EBV+ atMBCs may develop from EBV+ MBCs that are subsequently stimulated to express T-bet by IFNγ secreted by proximal T cells, possibly in response to unrelated infections." (PMID 36248899, 2022). "The high level of IFNγ and TNF cytokine expression indicates that ABCs may be functioning in a unique anti-viral capacity during latent infection." (PMID 36477199, 2022). "While the reasons are not clear, it is possible that despite being a latent infection, there could be periodic activity of some component (e.g. mRNA, protein) or low-level replication of Mtb that induces IFNγ production." (PMID 33584652, 2020). "During latent infection expression of viral UL111A (vIL-10) results in down regulation of MHC class II and diminished CD4+ T cell recognition and latent infection of CD34+ bone marrow progenitor cells induces release of cIL-10 and TGFβ which decreases CD4+ T cell IFNγ production and cytotoxicity." (PMID 24130479, 2013). "Similarly interferon gamma release assays (IGRA) which test for Th1 subset activation have failed to discriminate latent infection from recent exposure and have very little added value in an endemic setting." (PMID 21991356, 2011).
latent infection (continued). "Tuberculin skin test and interferon-gamma release assay are currently recommended for the diagnosis of LTBI, but have a marginal role in the detection of TB cases, as they cannot distinguish between active and latent infection and may be influenced by the patient’s immune status." (PMID 27808163, 2016). "Our results also revealed differences between IFNG and TNFA induction profiles and greater proportions of CD4+CD69+ T cells producing TNFA (but not IFNG) during active TB relative to latent infection." (PMID 30283456, 2018). "Similar to IFNγ in the IGRA, IP-10 was not able to differentiate between latent infection and active TB disease." (PMID 26771653, 2016).
Chagas disease (95 papers, 2009 to 2025). A parasitic infection caused by Trypanosoma cruzi. "In contrast, IFNG also has a central pathogenic role in Chagas disease by inducing heart damage through a variety of mechanisms." (PMID 37440604, 2023). "This creates a paradox, in that IFNγ is essential for control of parasitism in acute and chronic Chagas disease, but at the same time causes tissue damage." (PMID 32733459, 2020). "The inflammatory cytokine interferon-gamma (IFNγ) is crucial for immunity against intracellular pathogens such as the protozoan parasite Trypanosoma cruzi, the causative agent of Chagas disease (CD)." (PMID 25695249, 2015). "Higher levels of IFNγ and TNFα are associated with lower levels of IL-4 and IL-10, in both cardiac and more severe forms of Chagas disease, and high levels of IL-10 or moderate levels of IFNγ are associated with the indeterminate form." (PMID 24216069, 2013). "Chagas disease is associated with increased production of inflammatory cytokines; IFN-γ is a major pathogen resistance gene and plays a major role in the disease; T. cruzi infection of mice genetically deficient of IFNG leads to uncontrolled parasitism and 100% mortality." (PMID 32733459, 2020). "The involvement of these cells in the immunopathological mechanisms of the cardiac form of Chagas disease can be attributed to their cytotoxic effects, mainly because of the production of cytokines with a Th1 response profile such as interferon-gamma (IFN-γ)." (PMID 34489964, 2021). "The present study was designed to determine whether SNPs in IL12B, IL10, IFNG and IL4, key genes involved in the promotion and control of Th1 differentiation and IFN-g production to T. cruzi, are associated with Chagas disease outcome." (PMID 32733459, 2020). "Besides, pre-clinical models of Chagas disease have demonstrated that antigen-specific IFNγ+CD8+ T cells are essential for reducing parasite burden, increasing survival, and decreasing pathology in both the acute and chronic phases of disease." (PMID 29774028, 2018). "However, much less is known about the components of the IFNγ signal pathway that combat the etiologic agent of Chagas disease, and, conversely, how T. cruzi counteracts this attack." (PMID 25340519, 2014). "It was shown that IFNγ stimulus also upregulates the transcription factor T-bet, which in turn maintains IL-12Rβ chain expression, possibly resulting in a positive feedback loop that, consequently, keeps the shift towards a Th1 response in Chagas disease." (PMID 25120285, 2014). "Specifically, transforming growth factor β (TGF-β), tumor necrosis factor-α (TNF-α) and interferon gamma (IFN-γ) have also been proven to be key players in the immune response and pathogeny of Chagas disease." (PMID 39000409, 2024). "Specifically, transforming growth factor β (TGF-β), tumor necrosis factor-α (TNF-α), and interferon gamma (IFN-γ) are central to the immune response and pathology of Chagas disease." (PMID 32433643, 2020). "A recent study found higher levels of interferon-gamma, tumor necrosis factor-alpha, interleukin-10 and CCL3 in the myocardium of hamsters exhibiting acute symptoms of Chagas disease, when compared to asymptomatic animals." (PMID 20559542, 2010). "The core targets of plantain for treating gout are MAPK1, RELA, TNF, NFKBIA, and IFNG, and the key pathways are pathways in cancer, hypoxia-inducible factor-1 (HIF-1) signaling pathway, interleukin (IL)-17 signaling pathway, Chagas disease (American trypanosomiasis), and relaxin signaling pathway." (PMID 33149752, 2020). "In Chagas disease, the contribution of Pfn+ and IFNγ+ cells to heart injury has not been determined." (PMID 22532799, 2012). "In order to analyze whether the Chagas disease patients CD8+ T cells recognize the TcCA-2-derived peptides in the context of the HLA-A*02:01+ molecule, peptide-pulsed K562-A2 cells were used as APC in a multiplex immunoassay for detection of IFNγ secretion." (PMID 25816096, 2015).
lymphopenia (94 papers, 2011 to 2026). Reduction in the number of lymphocytes. "Taken together, these studies unequivocally demonstrated that decontrolled IFNγ signals are responsible, at least in part, for the onset of myeloproliferation and lymphopenia caused by A20 deficiency." (PMID 31477755, 2019). "CBCs and cytokine/chemokine analyses revealed transient lymphopenia and monocytopenia (only F331 model) on day 7 and a significant fold-increase of IFNγ, IL-6, MCP-1, MIG, and MIP-2 in mice that received Reg-1 KO B7-H3-CAR T cells." (PMID 40475601, 2025). "SLEV infection led to a reduction in total leukocyte counts in both WT and IFNγ-/- mice that was due to lymphopenia, similar to previous results with WT (SV129) and ABR-/- mice." (PMID 33410731, 2021). "Phenotypic analysis of the T cells showed increased frequency of CD44+ and significantly higher expression of Tbet and IFNγ in PTPN22 KO CD4 T cells after they underwent lymphopenia induced proliferation." (PMID 32047502, 2020). "Hyperinflammation may cause lymphopenia by inducing apoptosis, pyroptosis (both due to prolonged secretion of TNF-α, IL-6 or IL-18), or PANoptosis (due to the synergistic effect of IFNγ and TNF-α)." (PMID 39896810, 2024). "However, complement activation continues unabated, resulting in severe Lymphopenia and reduced interferon-gamma (IFN-γ) secretion." (PMID 35056603, 2022). "Furthermore, in the acute phase of MIS-C has been observed high levels of interleukin-1β (IL-1β), IL-6, IL-8, IL-10, IL-17, interferon-gamma (IFN-γ) and differential T and B cell subset lymphopenia." (PMID 33763085, 2021). "The explainable hypothesis for the difference of immune activity between HD and PD patients is that lymphopenia, decreased absolute counts of lymphocyte, and decreased production of interferon-gamma levels are more apparent in HD patients than in PD patients." (PMID 26392175, 2015). "Disease severity was associated with changes in innate monocytes and neutrophils, lymphopenia, disrupted cytokine production (increased IL-8 and IP-10/CXCL10 but reduced IFNλ2/3 and IFNγ), and increased endothelial injury (myoglobin, VCAM-1)." (PMID 37598150, 2023). "For examples, monocyte alterations (CD74, CIITA mRNA), lymphopenia (CD3, IL7R mRNA), increased anti-inflammatory response (IL10, IL1RN mRNA), altered IFN response (OAS2, IFNG mRNA) were observed." (PMID 36389738, 2022). "Lymphopenia-associated IL-7 overabundance contributes to the activation of naïve T cells, which undergo homeostatic or lymphopenia-induced proliferation (LIP) and convert into memory-like cells, which express high levels of CD44 and IFNγ." (PMID 27447484, 2016). "However, IFNγ expression was significantly increased in PTPN22 KO CD4 T cells indicating that PTPN22 influences the inflammatory potential of T helper cells and the difference between WT and KO was particularly pronounced in T cells of mice that underwent lymphopenia induced proliferation." (PMID 32047502, 2020). "The significant difference between SLE patients and HCs observed upon stimulation with the superantigen SEB, regarding IFNγ, IL17, and TNFα may indicate that leukocytes are generally dysfunctional in the SLE patients, also in those without lymphopenia, and unable to respond properly to the stimuli." (PMID 29499037, 2018).
toxoplasmosis (89 papers, 2009 to 2025). A parasitic disease contracted by the ingestion or fetal transmission of toxoplasma gondii. "According to the literature, toxoplasmosis is controlled by cellular immunity, so the authors evaluated the effect of the tested myrtus oil on chosen innate immunity mediators such as interferon gamma (IFN-γ) and IL-12." (PMID 37760822, 2023). "Together, these results highlight a stronger disease course of Toxoplasmosis with increased numbers of neutrophils, pDC activity, and effector T cell IFNγ production, all known to strongly influence the severity of diseases." (PMID 35898505, 2022). "Although IFNγ has long been identified as a critical cytokine to control toxoplasmosis, it is possible that exacerbated inflammation leads to detrimental effects." (PMID 33014898, 2020). "In summary, the absence of eIF4E phosphorylation appears to compromise host resistance against toxoplasmosis despite increased IFNγ production." (PMID 33014898, 2020). "Chronic resistance to toxoplasmosis requires a delicate balance between pro-inflammatory cytokines like IFNγ and TNFα to control infection and regulatory cytokines like IL-10 to prevent immunopathology." (PMID 22479310, 2012). "Interferon-gamma (IFN-γ) controls the different stages of toxoplasmosis." (PMID 34262559, 2021). "Interferon-gamma secreted in response to toxoplasmosis maintains this infection in a latent form because it induces astrocytes to synthetize indoleamine-2, 3-dioxygenase (IDO), the enzyme responsible for tryptophan degradation via the kynurenine metabolic pathway." (PMID 32132937, 2019). "In toxoplasmosis, recognition of parasitic profilin via toll like receptors 11 and 12 is one of the major signals triggering IL-12 production in DC which in turn induces IFNγ production by NK cells." (PMID 28845089, 2017). "Unraveling the parasite entirety of effectors necessary for survival in IFNγ stimulated cells is critical for our understanding of the mechanisms at play during infection and this knowledge could form the basis for developing strategies to combat toxoplasmosis more effectively." (PMID 39292011, 2024). "Because IL1β can enhance the IL12-mediated stimulation of IFNγ production and CD40–CD40L interaction can activate Toxoplasma destruction through autophagy, it is likely that GRA15 plays a role in human toxoplasmosis." (PMID 28278184, 2017). "A more recent study in a mouse model of toxoplasmosis identified the presence of a nonlymphoid source of IFNγ." (PMID 39324785, 2024).